APOE (apolipoprotein E)
Diseases named in the same sentence as APOE in open-access papers (continued):
Sharing a sentence is not in itself a finding about the gene and the disease.
atherosclerosis (continued). "Genetic depletion of eNOS leads to exacerbation of diet-induced atherosclerosis in the apolipoprotein E-knockout mouse model." (PMID 24662080, 2014). "Genetic deficiency in IFN-γ or its receptor in ApoE−/− mice reduced atherosclerotic lesion formation and enhanced plaque stability, whereas exogenously administered IFN-γ enhanced atherosclerosis in ApoE−/− mice." (PMID 25352848, 2014). "Nonetheless, the carotid lesions in ApoE−/− mice resemble advanced human atherosclerosis and represent the reproducible and reliable model for studies of vulnerable plaques." (PMID 24729664, 2014). "If the gene transfer strategy is used to achieve reversal of hypercholesterolemia, regression of atherosclerosis occurs only under sustained, high level ApoE expression, which is yet to be achieved in the clinical setting." (PMID 24741577, 2014). "Taken together, we newly found that there was an inverse relationship between miR-492 and resistin in apoE-null mice with pre-atherosclerosis pathological changes and insulin resistance." (PMID 24526524, 2014). "In contrast, ApoE(–/–) and TLR4(–/–) double-knockout mice were markedly more susceptible to atherosclerosis after oral infection with P. gingivalis, demonstrating an atheroprotective role for TLR4 in response to P. gingivalis infection." (PMID 24949459, 2014). "The objective of this study was to examine the effect of chronic ingestion of these H1-antihistamines on progression of atherosclerosis in ApoE−/− mice." (PMID 25020133, 2014). "Comparison of gene expression profiles obtained from pathogen treated mice at the acute and chronic time points was also examined to define how these pathogens modulate gene expression during the natural progression of atherosclerosis in ApoE-/- mice." (PMID 25540039, 2014). "With increase of oxidative stress in atherosclerosis, ApoE-KO mice showed accumulation of plaque area with increased IκBα degradation and NF-κB expression." (PMID 25397776, 2014). "We have conducted RCR analysis on gene expression datasets from a study utilizing the ApoE-/- mouse strain, a well-established model of atherosclerosis." (PMID 24965703, 2014). "ApoE knock-out mice were used as a classical atherosclerosis animal model, which exhibited various syndromes of atherosclerosis such as thicker vessel walls and foam cells formation." (PMID 24526524, 2014). "ApoE−/− mice spontaneously (i.e.: W group) went through accelerated changes in atherosclerosis progression over time which paralleled a rapid increase in liver inflammation around the 20 weeks of age." (PMID 24670925, 2014). "The extent and severity of atherosclerosis in 12-week apoE−/− mice with 6 weeks of diabetes are minimal and therefore beginning insulin at this time point corresponds to early treatment." (PMID 24829796, 2014). "A role for TLRs in high-fat-diet-induced atherosclerosis in animal models has been shown in studies using ApoE-/- TLR2-/- and ApoE-/- TLR4-/- mice." (PMID 25540039, 2014). "We have previously developed the apoE−/− mouse model in order to study the dyslipidemia-related renal injury and atherosclerosis." (PMID 24972137, 2014). "Treatment with resveratrol reduces atherosclerosis in hypercholesterolemic rabbits and in ApoE-KO mice." (PMID 25302702, 2014). "In LDL receptor knockout mice prone to atherosclerosis,ApoE mimetic peptides reduce plasma cholesterol and the extent of vascular lesions(Handattuet al, 2013)." (PMID 25172365, 2014).
atherosclerosis (continued). "This study aimed to evaluate the effects of GGDGT in a diabetic atherosclerosis model using apolipoprotein E knockout (ApoE-/-) mice fed a Western diet." (PMID 25416139, 2014). "Apolipoprotein‐E knockout (ApoE−/−) mice develop hypercholesterolemia and are a useful model of atherosclerosis." (PMID 25344475, 2014). "It has been reported that genetic disruption or pharmacological inhibition by telmisartan of the AT1R attenuates atherosclerosis and improves endothelial function in diabetic ApoE-/- mice via the PPARγ pathway." (PMID 24485356, 2014). "Study on the influence of microbiota showed that both conventional and germ-free kept mice with ApoE‒/‒ deficit on a high cholesterol diet had lesions of heavy atherosclerosis in thoracic and ventral aortas." (PMID 24741613, 2014). "For example, chronic unpredictable stress accelerates atherosclerosis in apolipoprotein E (apoE) knockout mice." (PMID 25189624, 2014). "The aim of this study was to further explore the impact of cola beverages drinking on the progression of arterial damagein the ApoE−/− mice model of atherosclerosis t different timeslong after discontinuation of cola beverages drinking-treatment." (PMID 24670925, 2014). "Recently, several expensive genetic animal models (such as ApoE gene knock-out mice or LDL-R gene-deficient mice) were used for human hyperlipidemia and atherosclerosis research." (PMID 25006576, 2014). "We imaged RAGE to investigate the effect of glucose control to suppress RAGE and reduce atherosclerosis in apolipoprotein E null (apoE−/−) diabetic mice." (PMID 24829796, 2014). "Apolipoprotein E knockout (apoE−/−) mice are a well-accepted animal model of hyperlipidemia, and have been used extensively to study the effects of this disease on atherosclerosis and renal injury." (PMID 24972137, 2014). "Infection of ApoE−/− TLR4−/− mice, fed a high-fat diet, with C. pneumoniae resulted in diminished atherosclerosis compared to ApoE−/− infected mice." (PMID 25010102, 2014). "Although studies have shown that sitagliptin can inhibit the formation of atherosclerosis in ApoE-/- mice, the mechanisms through which it attenuates the progress of atherosclerosis are complex and not completely understood." (PMID 24490809, 2014). "Oral infection of ApoE−/− mice with the P. gingivalis strain expressing antagonistic lipid A resulted in vascular inflammation, macrophage accumulation and atherosclerosis progression." (PMID 25010102, 2014). "Along these lines, the accelerated atherosclerosis in diabetic ApoE−/− mice was preceded by elevated blood monocytes and higher expression of endothelial activation- and inflammatory markers in the aorta." (PMID 23755169, 2014). "Long-term (five months) exposure of apoE−/− mice to nickel nanoparticles via inhalation accelerated the progression of atherosclerosis in the ascending aorta and enhanced the expression of related genes." (PMID 24590128, 2014). "The systemic effect observed in the BMAL1−/− model differed significantly from that in ApoE−/−, indicating that presumably the Bmal1−/− mice are less prone to the development of atherosclerosis compared to the dyslipidemic ApE−/− mice." (PMID 25394423, 2014). "To further investigate OEA's anti-atherosclerotic property, we fed ApoE−/− mice with HCD (HCD-ApoE−/− mice) to develop atherosclerosis, and examined atherosclerotic plaque formation under OEA administration (5 mg/kg/day, 14 wks, i.p)." (PMID 24465540, 2014). "Similar effect of RAGE expression on atherosclerosis was shown in apoE−/− db/db mice, a murine model of type II diabetes." (PMID 24829796, 2014). "Consumption of cola beverages, regardless sugar content, increased the rate of atherosclerosis progression in ApoE−/− mice favoring aortic plaque enlargement (inward remodeling) over media thinning." (PMID 24670925, 2014).
atherosclerosis (continued). "Confirming our earlier observations, the DKO control mice developed less atherosclerosis at the aortic sinus than their ApoE-null counterparts despite having a worse lipoprotein profile." (PMID 24587793, 2014). "Inhibition of atherosclerosis by atorvastatin in APOE*3Leiden.CETP mice has been observed previously." (PMID 25139399, 2014). "Stimulation of the PPARγ pathway, which promotes M2 macrophage polarisation, results in decreased atherosclerosis development in the ApoE-/- mouse." (PMID 25635207, 2014). "In this study we investigated effects of human (h)wt-PC, hS360A-PC, hwt-APC and hS360A-APC in acute (mouse model of acute myocardial ischemia/reperfusion (I/R) injury) and chronic inflammation (apoE−/− mouse model of atherosclerosis)." (PMID 25032959, 2014). "It is significant that the role of CD44 in inflammation has been described and demonstrated to be important for radiation-induced atherosclerosis in ApoE−/− mice." (PMID 25059316, 2014). "Periodontal bacteria were shown to accelerate the progression of atherosclerosis in ApoE knockout mice, rabbits, and pigs." (PMID 24949459, 2014). "The current study evaluated the interventional effects of a naturally occurring compound Notoginsenoside R1 (NR1) on atherosclerosis in ApoE−/− mice." (PMID 24933211, 2014). "The aim of this study was to investigate the effects of occlusal disharmony on the initiation of atherosclerosis in apolipoprotein E (apoE) knockout rats." (PMID 25189624, 2014). "We have investigated aortic endothelial cell calcium signalling changes in the Apolipoprotein E knockout mouse model of atherosclerosis." (PMID 25344475, 2014). "Conversely, a paradoxical protective effect of SCD on atherosclerosis and thrombosis was observed in ApoE-null mice transplanted with bone marrow from mice carrying the sickle cell mutation." (PMID 24847266, 2014). "In atherosclerosis-prone ApoE−/− mice and in human arterial specimens, the extent of atherosclerosis correlates with mtDNA damage." (PMID 24834056, 2014). "Infusion of angiotensin II induces aneurysm formation in mice prone to atherosclerosis (i.e., ApoE−/−, LDL−/−)." (PMID 24823865, 2014). "Apolipoprotein‐E knockout (ApoE−/−) mice, a widely used model of atherosclerosis, spontaneously develop hypercholesterolemia and atherosclerotic plaques when fed a normal diet." (PMID 25344475, 2014). "Another model to study atherosclerosis regression involves transplantation of plaque-containing portions of aorta from hypercholesterolemic ApoE−/− mice into normolipidemic C57BL/6 recipients." (PMID 24741577, 2014). "Infection of atherosclerosis-prone ApoE−/− mice with this strain resulted in progression of chronic inflammation in the vasculature." (PMID 25010102, 2014). "Here, we confirmed that apoE-null mice showed some pathology changes of pre-atherosclerosis in aortas endothelial cells, consisting with previous studies." (PMID 24526524, 2014). "The salient finding of the current study is that absence of PPARα gene prevents the aggravation of diet-induced atherosclerosis elicited by L-NAME in the ApoE-null mouse in vivo, independently of blood pressure or serum lipid alterations." (PMID 24587793, 2014). "Our results showed that CGA (400 mg/kg) significantly reduced atherosclerosis development and prevent aortic dilatation to a similar extent as atorvastatin in ApoE−/− mice." (PMID 25187964, 2014). "Stimulating CD137-CD137L interaction significantly increased CyPA, which was concurrent with the upregulation of proinflammatory cytokines, chemokines and matrix metalloproteinases and resulted in the promotion of atherosclerosis in ApoE-/- mice." (PMID 24520398, 2014). "The systemic inflammatory status of ApoE-/- mice, a well-established model of atherosclerosis, makes this strain an ideal model in which to study comorbidities associated to cigarette smoking." (PMID 24965703, 2014).
atherosclerosis (continued). "Our present aim was formally to test the requirement for T and B lymphocytes in M1 and M2 macrophage activation and MMP production using an established ApoE-KO mouse model of atherosclerosis formation." (PMID 25389425, 2014). "In advanced atherosclerosis model, in ApoE−/− mice, subendothelial infiltration of monocytes/macrophages and platelets was observed, evidenced by a positivity for CD163 and CD61 immunolabelling, in subendothelial space and in lipid accumulation sectors." (PMID 25328689, 2014). "In conclusion, our results presented here demonstrate that CGA potently reduces atherosclerosis development in ApoE−/− mice." (PMID 25187964, 2014). "Genetic disruption or pharmacological inhibition of the AT1R attenuates atherosclerosis and improves endothelial function in diabetic ApoE−/−-mice via the PPARγ pathway." (PMID 23374104, 2013). "We further studied the ability of Dunaliella to inhibit the progression of established atherosclerosis in old apoE−/− mice." (PMID 24175283, 2013). "ApoE−/− mice were treated with vehicle or Aldo infusion along with a high‐fat diet for 4 or 8 weeks, and the distribution of atherosclerosis in the aorta was examined." (PMID 23525413, 2013). "AT2 receptor deficiency and PD123319 administration have been used in several studies in apoE −/− mice to determine effects on atherosclerosis with variable results." (PMID 23593499, 2013). "We recently showed that TRAIL is protective against atherosclerosis, since a deficiency of TRAIL in ApoE−/− mice in response to a high fat diet (HFD) for 12 w, significantly increased arterial plaque area compared to ApoE−/− mice." (PMID 24040204, 2013). "The aim of this study was to investigate the influence of sildenafil on endothelial function and atherosclerosis progression in apolipoprotein E knockout (apoE−/−) mice." (PMID 23289368, 2013). "Individuals with defective isoforms of apoE, such as apoE4, develop postprandial hypercholesterolemia and atherosclerosis." (PMID 23984090, 2013). "In the present study we evaluated the capacity of a monoclonal antibody to B cell activating factor-receptor (BAFFR) to selectively deplete atherogenic B2 cells to prevent both development and progression of atherosclerosis in the ApoE−/− mouse." (PMID 23560095, 2013). "On the other hand, a recent investigation showed that inhibition of HA synthesis by treatment with 4-methylumbelliferone (4-MU) accelerated atherosclerosis in Western diet-fed apoE–/– mice." (PMID 23484050, 2013). "First, passive immunization with PC-specific T15 IgM antibodies reduced vein graft atherosclerosis in ApoE−/− mice." (PMID 23874490, 2013). "Together these findings are compatible with the notion that vitamin E treatment and ACE inhibitor treatment protected the aortic intima of atherosclerosis-prone ApoE−/− mice against ROS-mediated damage." (PMID 23801967, 2013). "Anti-BAFFR monoclonal antibody selectively depletes mature B2 cells while sparing B1a cells, disrupts spleen B-cell zones and ameliorates atherosclerosis development and progression in hyperlipidemic ApoE−/− mice." (PMID 23560095, 2013). "Over-expression of HSP27 is protective against the early formation of lesions in atherosclerosis-prone apoE−/− mice (apoE−/−HSP27o/e) - however, only in females." (PMID 23409070, 2013). "We now seek to determine if chronic HSP27 over-expression is protective in a model of advanced atherosclerosis in both male and female apoE−/− mice." (PMID 23409070, 2013). "Genetically-imposed hypercoagulability in TMPro/Pro:ApoE−/− mice resulted in severe atherosclerosis, plaque vulnerability and spontaneous atherothrombosis." (PMID 23409043, 2013).
atherosclerosis (continued). "In ApoE−/−mice, Nrf2 deletion resulted in atherosclerosis suppression, but with HO-1 deletion the atherosclerosis was accelerated." (PMID 23691261, 2013). "Apolipoprotein E deficient mice (Apo E) have an increased capacity for the intake of oxidized LDL into their macrophages, a hallmark of the early stages of atherosclerosis and foam cell formation." (PMID 24077237, 2013). "The results show that similar to LDL-R−/− mice, Dunaliella inhibits atherosclerosis in young apoE−/− mice and that the beneficial effects of the Dunaliella powder can be attributed to β-Carotene." (PMID 24175283, 2013). "Instillation of DEP produced similar increases in the total cell count in bronchoalveolar lavage fluid (BALF) from atherosclerosis-prone apoliprotein E knockout (ApoE−/−) mice to that from wild-type (C57bl6) mice (P < 0.03, unpaired t-test; n = 7-9)." (PMID 24330719, 2013). "ApoE plays an important role in atherosclerosis by modifying inflammatory responses and facilitating cholesterol efflux from foam cells." (PMID 23472151, 2013). "In contrast to LDL-R−/−, apoE−/− mice develop atherosclerosis on either low-fat or high-fat diet regimes." (PMID 24175283, 2013). "Although HDL-C contributed to some extent, we observed that niacin’s attenuating effect on atherosclerosis development in APOE*3Leiden.CETP mice, fed a Western-type diet with 0.1% cholesterol, is largely explained by its lipid-lowering effect." (PMID 23840481, 2013). "We have previously shown that TRAIL−/−ApoE−/− mice on a HFD for 12 w resulted in accelerated atherosclerosis when compared to ApoE−/− alone." (PMID 24040204, 2013). "The apoE production by tissue macrophages is crucial for the prevention of atherosclerosis and the aim of this study was to further elucidate how this apolipoprotein is regulated by cytokines present during inflammation." (PMID 24244577, 2013). "In contrast, treatment with bone marrow cells from older ApoE-/- mice with atherosclerosis is much less effective." (PMID 25984328, 2013). "To further investigate the role of GzmB and Prf1 in the development of atherosclerosis in ApoE KO mice, we generated GzmB/ApoE DKO and Prf1/ApoE DKO mice." (PMID 24205352, 2013). "ApoE KO mouse is a classical and commercial model widely used in the research of atherosclerosis and hyperlipidemia-induced peripheral organs injury." (PMID 23570453, 2013). "That oxidative stress apparent in atherosclerosis was affirmed in this study as the fat-fed ApoE−/− mice had significantly greater vascular superoxide generating capacity than the wild-type controls." (PMID 23864951, 2013). "ApoE is part of a gene cluster that is induced in macrophages by cholesterol-sensing nuclear receptors that protect against atherosclerosis in mice." (PMID 23792422, 2013). "The lesion development and plaque composition in ApoE KO mice are also similar to those in humans, establishing them as an excellent animal model for studying the pathogenesis of atherosclerosis." (PMID 24062791, 2013). "In conclusion, both Prf1 and GzmB contribute to the pathogenesis of atherosclerosis in ApoE KO mice." (PMID 24205352, 2013). "We also generated GzmB/ApoE double knockout (DKO) mice and Prf1/ApoE DKO mice to investigate the potential roles of these twoproteins in atherosclerosis." (PMID 24205352, 2013). "The AngII-infused ApoE−/− mouse model used in this study is a widely used animal model in atherosclerosis and aneurysm research." (PMID 23469284, 2013). "CD4+LAP+ Treg cells are a novel subset of Tregs that have been found to ameliorate atherosclerosis in ApoE−/− mice, and these cells also exist in humans." (PMID 24385687, 2013). "DHE staining showed that both treatment regimens normalized the increased superoxide generation of atherosclerosis-prone ApoE−/− aortas." (PMID 23801967, 2013). "The effect of Dunaliella on prevention of progression of atherosclerosis was studied in old apoE−/− mice with established atherosclerotic lesions fed a low- or high-fat diet." (PMID 24175283, 2013).